CT47A10 (cancer/testis antigen family 47 member A10)
Synonyms: CT47; CT47.10
Tractability: No criterion of Open Targets' tractability assessment is met for any kind of drug.
Gene: Protein-coding gene on chromosome X (120,938,701 to 120,942,023, reverse strand). Ensembl gene ENSG00000224089.
Subcellular location (Human Protein Atlas): Nucleoli
Homologues: Orthologues: macaque CT47B1 (77% identical). Paralogues in human: CT47A1 (100% identical), CT47A11 (100% identical), CT47A12 (100% identical), CT47A2 (100% identical), CT47A3 (100% identical), CT47A4 (100% identical), CT47A5 (100% identical), CT47A6 (100% identical), CT47A7 (100% identical), CT47A8 (100% identical), CT47A9 (100% identical), CT47B1 (86% identical), and 1 more.